SOX18 (SRY-box transcription factor 18)
Diseases named in the same sentence as SOX18 in open-access papers (continued):
Sharing a sentence is not in itself a finding about the gene and the disease.
pancreatic ductal adenocarcinoma (5 papers, 2019 to 2022). An infiltrating adenocarcinoma that arises from the epithelial cells of the pancreas. "Treatments induced apoptosis, increased BAX/BCL-2 ratio and suppressed the expression of SOX9 and SOX18, genes shown to be significantly up-regulated in pancreatic ductal adenocarcinoma." (PMID 35408514, 2022). "In pancreatic ductal adenocarcinoma, mir-7-5p targets sox18 to suppress cell proliferation, migration, and invasion." (PMID 33029099, 2020). "MiR-7-5p acts as a tumor suppressor in pancreatic ductal adenocarcinoma and suppresses cell proliferation, migration and invasion by targeting SOX18; in MCF-10A mammary epithelial cells, this miRNA suppresses oncogenes by mediating the signaling of hepatocyte growth factor." (PMID 30993031, 2019).
gastric cancer (4 papers, 2015 to 2025). A primary or metastatic malignant neoplasm involving the stomach. "The expression of SOX18 is associated with NKD2 methylation significantly in primary gastric cancer." (PMID 26396173, 2015). "In the case of SOX18, overexpression of SOX18 has been found in gastric cancer, as compared to normal gastric tissues." (PMID 26151573, 2015). "The results suggest that the expression of SOX18 is regulated by NKD2 in human primary gastric cancer." (PMID 26396173, 2015). "Above results suggest that NKD2 impedes cell invasion and metastasis by inhibiting SOX18 in gastric cancer." (PMID 26396173, 2015). "To further validate SOX18 is regulated by NKD2, we analyzed the association between SOX18 overexpression and NKD2 methylation in human primary gastric cancer." (PMID 26396173, 2015). "Additionally, an increased SOX18 protein concentration has been discovered in the blood serum of patients with gastric cancer." (PMID 33152990, 2020). "NKD2 suppresses gastric cancer metastasis by down-regulating SOX18 and its downstream genes." (PMID 26396173, 2015). "The expression of SOX18 was examined by IHC in 32 cases primary gastric cancer samples." (PMID 26396173, 2015). "Further study found that SOX18 promotes cell invasion and metastasis by down regulating MMP-2,7,9 in gastric cancer cells." (PMID 26396173, 2015). "Down-regulation of SOX18 by NKD2 was validated by RT-PCR and western blot in gastric cancer cells." (PMID 26396173, 2015).
infantile hemangioma (4 papers, 2019 to 2025). "Previous research from the Bischoff and Francois laboratories identified SOX18, an endothelial transcription factor, as a key target of propranolol therapy in infantile hemangioma." (PMID 40166936, 2025). "A SOX18-mevalonate pathway axis controls vascular overgrowth in infantile hemangioma revealing potential for statin therapy in this common vascular tumor." (PMID 39998898, 2025). "The R(+) enantiomer of propranolol and SOX18 small molecule inhibitor halt infantile hemangioma stem cell differentiation." (PMID 31358114, 2019). "Our previous findings suggested SOX18 as an attractive therapeutic target for KS and that this TF activity is directly modulated as part of R(+) -Propranolol off-target effects in the context of infantile hemangioma." (PMID 40894008, 2025). "In summary, we suggest the R(+) enantiomer of propranolol is a potent selective inhibitor of SOX18 activity and it is sufficient to achieve the effects of propranolol racemic mixture in the context of infantile hemangioma and other SOX18-dependent vascular diseases." (PMID 31358114, 2019). "(D) The effects of SOX18 inhibitor Sm4, its scaffold aspirin as a negative control, propranolol and its purified R(+) and S(-) enantiomers on HemSC-to-HemEC differentiation from two infantile hemangioma patients." (PMID 31358114, 2019). "In addition, the unexpected connection between SOX18 and the MVP prompted the question of whether blood vessels in infantile hemangioma could be suppressed by statins, as these drugs are competitive inhibitors of HMG-CoA-reductase and well known for their contributions to cardiovascular health." (PMID 40166936, 2025).
lung carcinoma (4 papers, 2012 to 2025). "Further investigation is necessary to fully understand the relationship between SOX18 and p21 in lung cancer and to explore the therapeutic potential of SOX18 inhibition in lung cancer." (PMID 37511076, 2023). "The transcription factor SOX18 has been shown to play a crucial role in lung cancer progression and metastasis." (PMID 37511076, 2023). "Our findings suggest a complex interplay between SOX18 and p21 in the context of lung cancer, and further investigation is necessary to fully understand the relationship between these two proteins in the disease." (PMID 37511076, 2023). "High methylation of SOX18 promoter has been reported in few studies, which partially explains the low levels of SOX18 mRNA found in lung cancer cohorts." (PMID 37511076, 2023). "Presently, the tumor suppressor characteristics of Sox proteins in lung cancer are mainly focused on members of Sox group F (Sox7, Sox17, Sox18)." (PMID 23443092, 2012). "To reinforce our hypothesis that SOX18 may have a role in regulation of p21 expression in lung cancer cells, we performed an assessment of IHC staining in clinical tissue samples obtained from lung cancer patients." (PMID 37511076, 2023). "Furthermore, our findings suggest a complex interplay between SOX18 and p21 in the context of lung cancer, with a positive correlation observed between SOX18 expression and p21 nuclear presence in clinical tissue samples obtained from lung cancer patients." (PMID 37511076, 2023). "Moreover, an increased expression level of the SOX18 protein has been found in many malignances, such as melanoma, stomach, pancreatic breast and lung cancers." (PMID 33152990, 2020). "Moreover, an increased expression level of the SOX18 protein has been found in several malignances, including melanoma, stomach, pancreatic, breast and lung cancers." (PMID 33152990, 2020). "Other than the Sox2 and Sox4, Sox9 and Sox18 also showed oncogenetic properties in lung cancer." (PMID 23443092, 2012). "The aberrant methylation in the promoter of Sox18 gene in lung cancer also suggested that inactivation of Sox18 expression might play a crucial role in the malignance." (PMID 23443092, 2012). "Unlike SOX18 expression, SOX7 expression has been shown to be decreased in lung cancers, which correlates with a poor patient prognosis." (PMID 33152990, 2020). "The role of the SOX proteins, including SOX18 and SOX30, in lung cancer is not very well known." (PMID 33152990, 2020).
melanoma (4 papers, 2019 to 2025). A malignant, usually aggressive tumor composed of atypical, neoplastic melanocytes. "Sox18 also appears to be involved in melanoma vascularization." (PMID 31073164, 2019). "In addition, we identified Mesenchyme (COL1A1+), Endothelium (SOX18+, KDR+), proliferating cells (TOP2A+, MKI67+), and some off‐target cells; Glial (MSX1+, SOX2+), Melanoma (PMEL+, PLP1+), and Neuron (DLL3, HES6)." (PMID 35322595, 2022).
primary lymphedema (4 papers, 2015 to 2025). A congenital condition that results in swelling in the arms or legs, and can occur during adolescence or adulthood. "Mutations of three genes, which are vascular endothelial growth factor receptor 3 (VEGFR-3), forkhead box C2 transcription factor (Foxc2), and SRY-box transcription factor 18 (SOX18), lead to primary lymphedema." (PMID 40244338, 2025). "Mutations in the transcription factor-coding gene SOX18, the growth factor-coding gene VEGFC and its receptor-coding gene VEGFR3/FLT4 cause primary lymphedema in humans." (PMID 37759531, 2023). "Several de novo mutations have also been identified in other genes mutated in microcephaly (i.e. CTNNB1 and TUBA1A) and in primary lymphedema, such as SOX18, FOXC2 and VEGFR3." (PMID 25934493, 2015).
bladder cancer (3 papers, 2023 to 2024). "For example, SLC12A5 can interact with and enhance SOX18 activity to promote bladder cancer progression via the NF‐κB/MMP‐7 pathway." (PMID 36645171, 2023).
liver cancer (3 papers, 2017 to 2025). An epithelial or non-epithelial malignant neoplasm that arises from the liver. "SOX18 promotes the accumulation of Tregs and immunosuppressive tumor-associated macrophages (TAMs) in the liver cancer microenvironment by transactivating PD-L1 and CXCL12." (PMID 39889187, 2025). "Seven TFs (FOXA1, FOXA2, RARG, STAT4, MEF2C, SOX18, and GXS2) have been identified to be likely to affect the metabolism, development, differentiation and proliferation of liver cancer in previous studies." (PMID 29033978, 2017).
prostate carcinoma (3 papers, 2019 to 2022). A carcinoma that arises from epithelial cells of the prostate gland. "Similarly, SOX18 can enhance cell migration and proliferation in both in vitro and in vivo models of prostate cancer by promoting the transcription of the pro-growth factors TCF1, c-Myc, and cyclin D1." (PMID 36620216, 2022).
congenital heart disease (2 papers, 2022). A heart disease that is present at birth. "Similarly, we have previously shown, through microarray analysis, that SOX18 is upregulated in the lungs of an ovine model of congenital heart disease that, results in increased pulmonary blood flow during a period of increased angiogenesis." (PMID 36620216, 2022).
Sepsis (2 papers, 2022 to 2025). Sepsis is defined as life-threatening organ dysfunction caused by a dysregulated host response to infection. "Conversely, we have found that in sepsis, Claudin-5 decreases in a SOX18-dependent manner leading to loss of barrier function and increased permeability." (PMID 36620216, 2022). "Additionally, SOX18 has been shown to have a protective role in sepsis, with its levels potentially serving as a prognostic marker for sepsis outcomes." (PMID 40093897, 2025). "This suggests that patients with sepsis-induced ARDS may already be experiencing a decreased expression of SOX18 and Claudin-5 before the initiation of mechanical ventilation." (PMID 36620216, 2022).
skin cancer (2 papers, 2022). "Two different studies indicated that SOX18, a transcription factor involved in endothelial cell differentiation, was upregulated in skin cancers whereas it was nearly absent in healthy skin samples." (PMID 35956111, 2022).
vascular neoplasm (2 papers, 2019 to 2025). A benign, intermediate, or malignant neoplasm arising from vascular tissue including arteries, veins, venous sinuses, lymphatic vessels, arterioles and capillaries. "Our work emphasizes the importance of SOX18 etiological role in vascular neoplasms, and suggests R(+)-propranolol repurposing to numerous indications ranging from vascular diseases to metastatic cancer." (PMID 31358114, 2019). "We further tested whether the SOX18-MVP axis is active in another pediatric vascular tumor, congenital hemangioma, with its sub-entities rapidly involuting and non-involuting congenital hemangioma (RICH and NICH)." (PMID 39998898, 2025).
acute lung injury (1 paper, 2022). A condition of lung damage that is characterized by bilateral pulmonary infiltrates (pulmonary edema) rich in neutrophils, and in the absence of clinical heart failure. "In acute lung injury (ALI), the NF-κB-mediated downregulation of Sox18 gene expression leads to the disruption of the pulmonary endothelial barrier." (PMID 35991176, 2022).
aortic aneurysm (1 paper, 2025). A ruptured aneurysm located in the wall of the proximal portion of the descending aorta proceeding from the arch of the aorta. "Nevertheless, the relationship between Sox18, EndMT and aortic aneurysm remained unexplored prior to our investigation." (PMID 41041074, 2025). "By focusing on ECs and analyzing published scRNA-seq datasets from human and mouse AAA samples, we characterized the transcriptional signatures and EC heterogeneity in aortic aneurysm, with particular attention to the role of Sox18 in EndMT during AAA development." (PMID 41041074, 2025). "Sox18 downregulation was confirmed in both human and mouse aortic aneurysm." (PMID 41041074, 2025).
arteriosclerosis (1 paper, 2020). A vascular disorder characterized by thickening and hardening of the walls of the arteries. "Additionally, it has been recently studied that the SOX18 protein can be involved in wound healing processes and arteriosclerosis disease progression." (PMID 33152990, 2020).
colon adenocarcinoma (1 paper, 2020). "SOX18 expression was also demonstrated in neoplastic lines of gastric, pancreatic and colon adenocarcinomas." (PMID 33152990, 2020).
glioma (1 paper, 2011). A benign or malignant brain and spinal cord tumor that arises from glial cells (astrocytes, oligodendrocytes, ependymal cells). "Taking together, SOX2 could act through SOX1 and SOX18, and thus play roles in both maintaining stem cell properties of glioma cells and forming tumor vasculature in gliomas, which are two major obstacles preventing us from treating these tumors effectively." (PMID 21211035, 2011).
growth disorders (1 paper, 2021). "Interestingly, multiple sox family members (sox5, sox6, sox8, and sox18) were significantly dysregulated in shox-deficient pectoral fins together with other genes (nppa, nppc, cdkn1a, cdkn1ca, cyp26b1, and cy26c1), highlighting an important role for these genes in shox-related growth disorders." (PMID 34122528, 2021).
idiopathic pulmonary arterial hypertension (1 paper, 2020). A sporadic form of pulmonary arterial hypertension (PAH) characterized by elevated pulmonary arterial resistance leading to right heart failure. "In particular,SOX18 was implicated through bioinformatics analyses inregulating the idiopathic pulmonary arterial hypertension endothelial celltranscriptome." (PMID 32166015, 2020). "Several transcription factors were also found to beupregulated in idiopathic pulmonary arterial hypertension endothelial cellsincluding SOX18, STRA13, LYL1, and ELK, whichhave known roles in regulating endothelial cell phenotype." (PMID 32166015, 2020).
Intellectual disability (1 paper, 2023). "It should be noted that both MEF2C and RBPJ have been associated with intellectual disability and seizure disorders, matching the SOX18 E137K Geno2MP neurological phenotypes." (PMID 36672963, 2023).
invasive ductal breast carcinoma (1 paper, 2025). The most common type of invasive breast carcinoma, accounting for approximately 70% of breast carcinomas. "In human invasive ductal breast carcinoma, sex-determining region Y (SRY)-box transcription factor 18 (SOX18) expression correlates positively with VEGF-D, indicating a possible role of SOX18 in the lymphangiogenesis process." (PMID 41511312, 2025).
laryngeal carcinoma (1 paper, 2019). Carcinoma that arises from the laryngeal epithelium. "An increase in SOX18 level was observed in laryngeal carcinoma tissues compared with the adjacent normal tissues (P<0.01)." (PMID 31189744, 2019). "Initial findings indicate that the expression of SOX18 was increased in laryngeal carcinoma cell lines and tissues." (PMID 31189744, 2019). "Overexpression of SOX18 was found in the tumor tissues of laryngeal carcinoma patients, which regulated cell proliferation, migration, and invasion of laryngeal carcinoma cells through JAK2/STAT3 signaling." (PMID 31189744, 2019). "The results revealed that SOX18 promoted carcinogenesis in laryngeal carcinoma via activating JAK2/STAT3 signaling." (PMID 31189744, 2019). "The aim of the present study is to explore the biological function of SRY-related HMG-box 18 (SOX18) in laryngeal carcinoma cells and study the molecular mechanism involved." (PMID 31189744, 2019). "The findings revealed that SOX18 was a critical regulator, which is involved in human laryngeal cancer." (PMID 31189744, 2019). "In the present study, laryngeal cancer tissues and adjacent normal tissues were collected for the detection of SOX18 expression." (PMID 31189744, 2019). "The expression of SOX18 was significantly increased in laryngeal cancer cell lines compared with that in BEAS-2B cells (P<0.01)." (PMID 31189744, 2019). "The results indicated that down-regulation of SOX18 significantly inhibited cell proliferation, migration, and invasion, and induced cell-cycle arrest in G0/G1 phase and apoptosis of laryngeal carcinoma cells." (PMID 31189744, 2019). "SOX18 knockdown significantly weakened cell migration and overexpression of SOX18 remarkably increased cell migration in laryngeal carcinoma cell lines (P<0.01)." (PMID 31189744, 2019). "The effect of SOX18 on laryngeal carcinoma cell proliferation, cell cycle, apoptosis, invasion, and migration was also identified." (PMID 31189744, 2019). "It was initially found that the expression of SOX18 was increased drastically in laryngeal cancer tissues compared with normal tissues." (PMID 31189744, 2019). "For laryngeal carcinoma cell invasion, siSOX18 could notably inhibit cell invasion, and up-regulation of SOX18 could significantly promote cell invasion in laryngeal carcinoma cell lines (P<0.01)." (PMID 31189744, 2019). "The results showed that siSOX18 effectively decreased cell migration and invasion capability, and SOX18 could promote cell migration and invasion in laryngeal carcinoma cells." (PMID 31189744, 2019). "To conclude, our research suggested that targeting SOX18 might provide a novel treatment strategy for laryngeal carcinoma." (PMID 31189744, 2019). "Furthermore, mRNA expression of SOX18 in laryngeal cancer cell lines (SNU899, TU212, and Hep-2) and normal bronchial epithelial cell line (BEAS-2B) were also evaluated by qRT-PCR." (PMID 31189744, 2019). "SOX18 was also overexpressed in laryngeal cancer cell lines." (PMID 31189744, 2019). "The results showed that SOX18 might act as an oncogene in the occurrence and progression of laryngeal carcinoma." (PMID 31189744, 2019). "In addition, it was found that SOX18 could also accelerate the phosphorylation of JAK2/STAT3 signaling in laryngeal carcinoma cells." (PMID 31189744, 2019). "Furthermore, it was found that SOX18 may also promote the occurrence and development of laryngeal carcinoma." (PMID 31189744, 2019). "The results revealed that SOX18 could function as an oncogene in laryngeal carcinoma." (PMID 31189744, 2019). "The role and mechanism of SOX18 in laryngeal carcinoma still remains unclear." (PMID 31189744, 2019). "Consequently, we demonstrated that SOX18 was overexpressed in laryngeal carcinoma cell lines and tissues, and regulated the cell proliferation, cell cycle, apoptosis, migration, and invasion of laryngeal carcinoma cells via JAK2/STAT3 signaling." (PMID 31189744, 2019).
laryngeal carcinoma (continued). "Furthermore, our study indicated that SOX18 could stimulate cell proliferation, migration, and invasion of laryngeal carcinoma cells via regulation of JAK2/STAT3 signaling, which could provide a new strategy for laryngeal carcinoma diagnosis and molecular therapies." (PMID 31189744, 2019).